PLK1 (polo like kinase 1)
Diseases named in the same sentence as PLK1 in open-access papers (continued):
Sharing a sentence is not in itself a finding about the gene and the disease.
cancer (continued). "Plk1 is only expressed occasionally in normal thyrocytes while overexpressed in the bulk of microcarcinomas, smaller PTC, ATCs, and incidental carcinomas, which may support the assumption that Plk1 makes a constitutive effect on PTC in the early stage." (PMID 38260150, 2023). "PLK1 is a promising target under clinical investigation in TNBC and several other cancers." (PMID 35454120, 2022). "It was the first pioneered PLK1 inhibitor to enter clinical trials for the treatment of cancer, however it was not very effective during monotherapy regimens in clinical trials." (PMID 36297281, 2022). "The polo-like kinase (PLK) family (e.g., PLK1-5) plays a fundamental role in the pathogenesis and progression of tumors; however, limited studies have explored the value of PLK5 in cancer." (PMID 36684318, 2022). "Based on three microarray gene profiling datasets from the Gene Expression Omnibus (GEO) and RNA-Seq expression data from The Cancer Genome Atlas (TCGA), Mitotic Spindle Positioning (MISP or C19orf21), a substrate of Plk1, was found to be up-regulated in many types of cancer." (PMID 35433491, 2022). "Finally, the identification of additional substrates of PLK1 during SAC activation and normal cell cycle progression will herald the development of new approaches for treating diseases such as cancer." (PMID 35563642, 2022). "Up to this point, it is also interesting to note that most of the GO and KEGG terms based on the DEGs like CCNB1, PLK1 and CDC20 are closely related to anti-cancer patterns, which may point to the anti-cancer potential of our MOL extract preparation." (PMID 36197921, 2022). "Remarkably, PLK1 and XPO1 have been reported to be selectively required for KRAS-mutant cancers by counteracting mitotic and nuclear export stress associated with KRAS-induced tumorigenesis, and our recent study has implicated PLK1 in metabolic stress response of KRAS-mutant cancers." (PMID 35039048, 2022). "Analysis of the various cancers revealed that several putative REST target genes, including Polo Like Kinase 1 (PLK1), ADAM Metallopeptidase Domain 12 (ADAM12), Troponin T1 (TNNT1), and cell migration-inducing and hyaluronan-binding protein (CEMIP, KIAA1199) were highly dysregulated." (PMID 35177031, 2022). "Thus, Plk1 and AKA are considered to be attractive targets for cancer therapy in solid tumors, myeloid leukemias, and myelodysplasias." (PMID 35159005, 2022). "Analysis of PLK1 mRNA levels by qRT-PCR demonstrated that PLK1 was overexpressed in both cancer cell lines tested when compared to the non-tumor cell line HPAEpiC." (PMID 35745782, 2022). "Notwithstanding, it remains to be elucidated if these cancers are more sensitive to PLK1 inhibition than cancers with normal expression levels of PLK1." (PMID 35745782, 2022). "Improved cytotoxicity was obtained when gatastatin was given in combination with polo-like kinase 1 (PLK1) inhibitors, suggesting that this combination may have therapeutic efficacy in cancer treatment." (PMID 36188585, 2022). "Namely, FOXM1 promotes epithelial-mesenchymal transition and metastasis formation for breast and various other cancers, RRM2 contributes to poor survival and tamoxifen resistance development, while expression levels of CDK1, PLK1 and RACGAP1 were shown to be prognostic markers." (PMID 33852600, 2021). "PLK1 phosphorylates TSC1 and functions as a positive upstream regulator of mTORC144,45, whereas it phosphorylates Raptor, inhibits mTORC1, and thereby induces autophagy in interphase cancer cells." (PMID 34675258, 2021). "In the end, the molecular function of Cdc20 in pan-cancer analysis indicated that BUB1, CCNA2, CCNB1, CDK1, MAD2L1, and PLK1 might play a critical role in its oncogenic function." (PMID 34527589, 2021). "In subsequent pharmaceutical efforts, new PLK1 inhibitors such as GSK461364A, and PHA-680626 were all developed to inhibit PLK1 with low nanomolar IC50s and exert potent antiproliferative effects on various cancer cells." (PMID 33917995, 2021).
cancer (continued). "Cluster 1 has the maximum score 27.676, with 38 nodes and 512 edges, including known cancer-related genes, such as BUB1 (mitotic checkpoint serine/threonine-protein kinase BUB1), CDC20 (cell division cycle protein 20 homolog), and PLK1 (serine/threonine-protein kinase PLK1)." (PMID 34512870, 2021). "Plk1 expression depends, at least in part, on HIF-1, HIF-1 and HIF-2, or HIF-2 in most cancers." (PMID 33547392, 2021). "Several mitotic kinases, Aurora A, polo-like kinase 1 (PLK1) and NIMA-related kinase 2 (NEK2), were shown to block assembly and induce disassembly of the primary cilium, and upregulated activity of these kinases is frequently found in cancer." (PMID 34207779, 2021). "We showed that fostamatinib (which can target PLK1 and other over-expressed serine/threonine kinases such as AURKA, MELK, NEK2, and TTK) is more active against cancer lines with more pronounced signatures of invasion (e.g., extracellular matrix organization/degradation)." (PMID 34680307, 2021). "PLK1 was widely studied as a target in cancer therapy while residued relative low expression level in normal cells." (PMID 33648590, 2021). "Hence, it is important to investigate the effects of PLK1, ATM and ALDOA on the DDR and the potential value of these proteins as targets in cancer therapy." (PMID 34565365, 2021). "Resveratrol may inhibit cell cycle at G1/ S phase in MCF7 and MDA- MB231 cancer cells through targeting Aurora protein kinase (AURKA) and the Polo-like kinase-1 (PLK1) pathways." (PMID 32952942, 2020). "First, we sought to identify at least one PLK1-derived CD8 T-cell epitope that could be naturally processed and presented on tumour cells, and thus be used for a peptide-based cancer therapy." (PMID 32595211, 2020). "Overall, PLK1 inhibition has not had success as a targeted cancer therapy despite high anticipation arising from promising pre-clinical investigations." (PMID 33066048, 2020). "PLK1 has been the subject of much pre-clinical and clinical studies, but thus far, PLK1 inhibitors have not shown significant improvement in cancer patients." (PMID 33066048, 2020). "Although treatment of TGF-β or active PLK1 upregulates TSG6 expression, the depletion of TSG6 reduced the levels of PLK1 or TGFB1, suggesting that TSG6 and PLK1 or TGFB1 could mutually trigger their expression for cancer metastasis." (PMID 31548612, 2020). "These experimental results suggest that targeting mitotic oncogenic factors, such as PLK1 and USP7, may be effective for treating carcinomas that have resistance to mitotic catastrophe." (PMID 33207738, 2020). "On the contrary, other Plk1 depletion studies done in different Plk1-modified mice strains showed that reduced levels of PLK1 do not alter mouse viability in terms of cancer appearance." (PMID 30862113, 2019). "Although Plk1 has been shown to play an indispensable role in cell cycle and mitotic progression of non-myogenic cell types especially cancer cells, its function in MuSCs and myogenesis has not been investigated." (PMID 31393265, 2019). "Gene expression analysis revealed that its mechanism of action might be attributed, in part, to downregulation of cancer-related genes, such as AKT1, BCL2L1, CCND1, CDK4, PLK1, and RHOA." (PMID 31527550, 2019). "On the contrary, Estrogen Receptor-negative (ER−) and Her2 amplified (Her2+) cancer patients, that have higher levels of Plk1, present a significantly improved RSF outcome." (PMID 30862113, 2019). "For example, the inhibition of PLK1, a major mitotic kinase, selectively eradicates cancer cells, but not normal cells, through mitotic cell death." (PMID 29976159, 2018). "As the stability of BEX4 was regulated by PLK1 activity, we examined whether ectopic expression of BEX4 induces polyploidy in cancer cells." (PMID 30367032, 2018).
cancer (continued). "For one thing, AZD1775-reduced PLK1 may contribute to AZD1775-induced DNA damage and apoptosis still presented in WEE1 CRISPR-Cas9 knockout cancer cells, in line with reliance of AZD1775’s cytotoxicity on targeting PLK1 and WEE1 in our GC cells." (PMID 29954437, 2018). "Further search for regulators of biosynthesis during cell cycle progression led us to the identification of Plk1 as a master regulator of pentose phosphate pathway (PPP), a major biosynthesis pathway whose aberrant activation was described in various cancer cells." (PMID 29138396, 2017). "Collectively, these data demonstrate that Plk1 enhanced PPP and biosynthesis in cancer cells." (PMID 29138396, 2017). "Furthermore, the results confirmed that the regulation of RSK1 by Plk1 differed between MKN45/MKN74 CSC-like cells and cancer cells." (PMID 28430578, 2017). "Although PLK1 is over-expressed in a variety of cancer cells, PLK1 is vital for cell proliferation regardless of normal or malignant cells." (PMID 29108241, 2017). "Given the crucial role of PLK1 in cell-cycle regulation and DNA damage repair, it is not surprising that it is overexpressed in a variety of malignant neoplasms such as non-small cell lung cancer, bladder cancer, and colorectal cancer." (PMID 28915707, 2017). "The FOXM1 transcription factor is a proto-oncogene involved in cell cycle progression, cell proliferation, tumorigenesis and cancer progression, and many of its target genes (> 20) were downregulated in paclitaxel-residual MDA-MB-231 cells including AURKB, CCNB1, PLK1, PLK2, and the kinesin KIF20A." (PMID 28187446, 2017). "Increasing evidence supports that PLK1 has multiple non-mitotic functions, especially in cancer cells." (PMID 29246203, 2017). "Plk1 activity did not change in response to inhibition of RSK1 in the cancer cells, but increased in the CSC-like cells." (PMID 28430578, 2017). "Importantly, we further demonstrate that Plk1-mediated activation of G6PD is critical for its role to promote cell cycle progression and cancer cell growth." (PMID 29138396, 2017). "Thus, we implicate the protein-protein interactions of PLK1 and PLK4 in the maintenance of mutant KRAS-expressing cancers, and illustrate the use of compounds that block these interactions in single-agent or combination therapies." (PMID 28807782, 2017). "PLK1 expression is higher in cancer cells than in nontransformed cells, and promotes G1/S transition and DNA replication in addition to the G2/M phase transition." (PMID 28036269, 2017). "Furthermore, western blot analysis showed that phosphorylation of Plk1 was significantly increased in the CSC-like cells after treatment with RSK1 inhibitors, in contrast with the cancer cells." (PMID 28430578, 2017). "Other studies have shown that various cancer cells—but not their isogenic normal cells—are addicted to Plk1 overexpression for their viability." (PMID 28721210, 2017). "To further identify the capability of PLK1 in discriminating cancer from non-cancerous gastric tissues, we generated a summary receiver operating characteristic (SROC) curve and then calculated the area under the curve (AUC)." (PMID 29190933, 2017). "Importantly, regulation of Plk1 and RSK1 differed between gastric CSC-like cells and the cancer cells." (PMID 28430578, 2017). "In this study, we examined that combining PLK1 inhibitor with tumor necrosis factor-related apoptosis-inducing ligand (TRAIL) would have an additive and synergistic effect on induction of apoptosis in cancer cells." (PMID 29186071, 2017).
cancer (continued). "In our combinatorial screening, combined PLK1/ROCK inhibition with BI-2536 and fasudil emerged as a top hit and exhibited a strong ability to induce apoptosis and cell cycle arrest in KRAS-mutant cancer cell lines." (PMID 27193833, 2016). "Indeed, several PLK1 inhibitors, including BI2536 and GSK461364, are in clinical studies for treating patients with various cancers." (PMID 26799423, 2016). "High PLK1 expression has been described in many forms of cancer, yet its role in DIPG tumorigenesis has not previously been explored." (PMID 27538997, 2016). "Several synthetic lethality screens have been performed on KRAS mutant cancer cell lines to determine potential targets, and results have frequently included genes important in cell cycle progression or mitosis, such as CDK1, cyclin A2, PLK1, and CDC6." (PMID 27167191, 2016). "In addition, several hits, including PLK1, PRKAA1 (or AMPK), PIK3CG and ERBB3 have also been previously shown to mediate cancer cell survival and growth, independently validating the results of our screen." (PMID 27192118, 2016). "Recent evidence suggests that PLK1 also has other roles in cells, but it is not clear how much they contribute to the development of cancer." (PMID 27003818, 2016). "Further study of this type of combination (for example, the dual inhibition of PLK1 and ROCK) against KRAS-mutant cancers in clinical trials may be warranted." (PMID 27193833, 2016). "Moreover, it is involved in tumorigenesis through the activation of PLK1, BUB1B and C-MYC, and repression of CDKN1B during cancer progression." (PMID 27270442, 2016). "PP2A inhibition-induced sensitization to radiation and chemotherapy in cancer cells is believed to occur via several mechanisms, including sustained phosphorylation of Akt, MDM2, Plk1, TCTP and Cdk1, which are involved in apoptosis, cell cycle deregulation, and inhibition of DNA repair." (PMID 27527863, 2016). "Here, we show that four different classes of Plk1 inhibitor block mitotic entry in several cancer cell lines and non-transformed RPE-1 cells." (PMID 26472023, 2015). "Polo-like kinase 1 (PLK1), a serine/threonine kinase identified as a potential drug target in cancer therapy, may also affect NEK2A activity in cancer cells, albeit indirectly." (PMID 25705694, 2015). "Additionally, it has been described that HDAC inhibitors (HDACi) reduce Plk1 protein, suggesting the combination of Plk1 and HDAC inhibitors to combat cancer." (PMID 26317649, 2015). "Since both Plk2 and Plk3 are required for promoting cell survival and they exhibit properties similar to tumor suppressors, specific inhibition of Plk1, but not Plk2 or Plk3, would be important for selectively killing cancer cells, but not normal cells." (PMID 26500787, 2015). "PLK-1 is the most promising mitotic kinase validated as a chemotherapeutic cancer target because PLK-1 is critically essential for cancer cell survival and not for normal cells." (PMID 26557691, 2015). "From earlier studies it is known that Plk1 depletion leads to different effects in cancer vs. non-cancer cells, and thus we analyzed this combination in cancer and non-cancer cells to confirm these differential effects." (PMID 26317649, 2015). "The (si)RNA-mediated depletion of PLK-1 arrests tumor growth and triggers apoptosis in cancer cells without affecting normal cells." (PMID 26557691, 2015). "Thus, a strategy in the treatment of cancer has been to target the kinase activity (ATPase domain) or substrate-binding domain (Polo-box Domain, PBD) of Plk1." (PMID 25036740, 2014).
cancer (continued). "In addition, transfection of constitutively active AKT or PLK1 partially rescued cells from 15d-PGJ2-induced apoptosis, suggesting crucial roles for both pathways in the anti-cancer effects of 15d-PGJ2." (PMID 24566468, 2014). "Our results are in agreement with previous data showing that absence of other mitotic regulators, such as PLK1 or Aurora kinase family members, affects preferentially cancer cell proliferation." (PMID 23700430, 2013). "It was recently reported that PLK1 knockdown using RNAi only results in a strong mitotic arrest in cancer cells and not in non-cancer cell lines." (PMID 23056340, 2012). "The expression of Plk1 in normal cells is not nearly as strong as that in cancer cells, which makes Plk1 a discriminating tartget for the development of cancer-specific small molecule drugs." (PMID 23227884, 2012). "Not surprisingly, deregulation of Plk1 is often found in many types of cancer, including melanoma, lung, head and neck, breast, and ovarian cancer with poor prognosis." (PMID 22852086, 2012). "Raab and his colleagues found that the primary cells’proliferation, spindle assembly and apoptosis exhibited only a low dependency on Plk1 in contrast to the addiction of many cancer cell lines to the non-oncogene Plk1." (PMID 23151088, 2012). "It is tempting to speculate that a combined therapy using inhibitors of both Plk1 and PARP may be an effective approach to improve prognosis of BRCA-defective cancers." (PMID 22325354, 2012). "Initial motivation for developing inhibitors of PLK1 as candidate cancer drugs was the potential to avoid the toxicities of traditional antimitotics that target tubulin structures equally in both cancer and nondividing cells." (PMID 22248814, 2011). "PLK1 siRNA based studies have suggested that Plk1 depletion did not affect normal cells or was much less effective in normal cells, as compared to cancer cells." (PMID 20886032, 2010). "In direct comparisons normal cells did not appear to be affected by Plk1 depletion, whereas cancer cells arrested in mitosis followed by cell death." (PMID 20886032, 2010). "ON01910, a non-ATP-competitive Plk1 inhibitor, was reported to inhibit cancer cells growth by inducing mitosis arrest and apoptosis in many tumor cell lines." (PMID 19216791, 2009). "This may be related to the fact that PLK1 is not preferentially expressed in the cancer stem cell (CSC) or cancer initiation cell (CIC) population." (PMID 40612941, 2025). "However, how LAS affects PLK1 expression and whether LAS exerts its anti-cancer activities via regulating other pathways, or shares imilar molecular mechanisms with Isodon rubescens are worthy of further investigations." (PMID 38495493, 2024). "Associations between PLK1 and TIME in all cancer types have not been thoroughly studied." (PMID 36951624, 2023). "Although PLK1 inhibitors show robust anticancer activity in animal models, they have been plagued by dose-limiting toxicity in clinical trials and none have been approved as cancer drugs to date." (PMID 37049713, 2023).